CHCT1 (CHD1 helical C-terminal domain containing 1)
Description:
May play a role in regulation of apoptosis.
Synonyms: C17orf64
Tractability: PROTAC: ubiquitination databases record sites on it.
Gene: Protein-coding gene on chromosome 17 (60,392,429 to 60,431,426, forward strand). Ensembl gene ENSG00000141371.
Subcellular location: Cytoplasm; Nucleus
Subcellular location (Human Protein Atlas): Nucleoplasm; Vesicles
Gene Ontology:
Cellular component: nucleus; cytoplasm
Genetic constraint (gnomAD): Loss-of-function variants: 34 observed, 28.23 expected, observed/expected ratio (o/e) 1.2, 90% interval 0.92 to 1.6. The upper end of that interval is the gene's LOEUF score, 1.6, which puts it in group 6 of 6, group 1 being the genes least tolerant of losing a copy. Missense variants: 264 observed, 280.73 expected, observed/expected ratio (o/e) 0.94, 90% interval 0.85 to 1.04. Synonymous variants: 105 observed, 111.37 expected, observed/expected ratio (o/e) 0.94, 90% interval 0.8 to 1.11.
Homologues: Orthologues: chimpanzee CHCT1 (98% identical), macaque CHCT1 (92% identical), dog CHCT1 (76% identical), rabbit CHCT1 (73% identical), mouse Chct1 (73% identical), rat Chct1 (69% identical), guinea pig CHCT1 (63% identical).
Diseases named in the same sentence as CHCT1 in open-access papers:
CHCT1 is named in the same sentence as 2 diseases in open-access papers, as found by Europe PMC text mining. Sharing a sentence is not in itself a finding about the gene and the disease.
CHCT1 shares sentences with these, for which no sentence is quoted: breast carcinoma (1 paper); serous ovarian carcinoma (1).